INS (insulin)
Diseases named in the same sentence as INS in open-access papers (continued):
Sharing a sentence is not in itself a finding about the gene and the disease.
type 2 diabetes (continued). "Recent studies have demonstrated that the islet-restricted zinc transporter, ZnT8 (SLC30A8), regulates insulin secretion and hepatic insulin clearance, suggesting that Zn is a key biological factor in glucose homeostasis and the risk of developing type 2 diabetes." (PMID 27895622, 2016). "However, ZDF rat is an obese type 2 diabetes model with a point mutation in the leptin receptor, which makes it an ideal model for studying insulin resistance related to obesity." (PMID 27069931, 2016). "Loss of insulin pulsatility is an early event in the development of type 2 diabetes." (PMID 27788129, 2016). "PUFA may also help counter toxicity of tissue free fatty acids; and increase membrane fluidity, which might augment insulin sensitivity and lower risk of type 2 diabetes." (PMID 27434027, 2016). "Because type II diabetes is caused by decreased insulin sensitivity due to excess lipids accumulated in skeletal muscle tissue, lipidomic analysis of muscle tissues under treadmill exercise can help unveil the mechanism of lipid-associated insulin resistance." (PMID 27388225, 2016). "Roumie and colleagues have reported that the addition of insulin to existing metformin treatment was associated with an increased risk of cardiovascular events and all-cause mortality versus the addition of sulfonylurea in people with type 2 diabetes." (PMID 27152598, 2016). "Because chronic fructose intake is associated with impaired insulin signaling, it could facilitate the disruption of glucose homeostasis and the transition of prediabetes to type 2 diabetes through Txnip." (PMID 27725089, 2016). "Our findings may explain the previous observation that chronic infusion of MG reduces insulin secretion and the development of type 2 diabetes in SD rats and expand the underlying mechanisms of MG-induced impaired insulin secretion." (PMID 26779540, 2016). "The strong correlation between the 1-h glucose concentration and reduced insulin sensitivity may explain why the 1-h glucose could be a better risk predictor for future type 2 diabetes compared with fasting or 2-h glucose concentrations." (PMID 27274905, 2016). "Moreover, via upregulation of IL-6 and osteopontin, TLR2 causes impaired insulin-mediated brain activities, which are an early step in the development toward type 2 diabetes." (PMID 28536605, 2016). "Certain vitamin D binding proteins and allelic variations in the vitamin D receptor gene might also affect insulin secretion and glucose tolerance, which, in turn, might contribute to the genetic risk of type 2 diabetes." (PMID 27413370, 2016). "In this respect, a better comprehension of the gene networks that interact with HNF1A/MODY3 could be extremely useful in dissecting the molecular aspects underlying the variability of insulin secretion defects in type 2 diabetes." (PMID 27667715, 2016). "To further elucidate this association, we also included type 2 diabetes patients using insulin." (PMID 27887576, 2016). "These defects in combination with other weaknesses already present in the insulin-signaling pathway in diabetic-proned patients might explain much of the reported increased risk of developing type 2 diabetes in rosuvastatin treated patients." (PMID 26986474, 2016). "Defective insulin secretion exemplified by impaired GSIS is a hallmark of type 2 diabetes." (PMID 27265727, 2016). "Several lines of evidence indicated that diverse risk factors for type 2 diabetes such as overweight, physical inactivity and abdominal obesity can induce insulin resistance, a condition in which the body cells fail to respond effectively to insulin." (PMID 26819084, 2016). "Signaling pathways regulating myofiber type, mitochondrial biogenesis and oxidative capacity in the skeletal muscle, which collectively are linked with muscle insulin sensitization, are of great interest for informing therapeutic development in type II diabetes." (PMID 28005939, 2016).
type 2 diabetes (continued). "Patients developing type II diabetes have often gone through a state of obesity associated with reduced insulin sensitivity along with an activated beta cell compensatory mechanism, such as excess basal insulin secretion and hyperinsulinemia, as a part of their metabolic profile." (PMID 26880906, 2016). "The aim of the present study was to examine whether elevated anxiety symptoms, elevated depressive symptoms, or both, are associated with increased risk of mortality during 17 years follow up in insulin naïve people with Type 2 diabetes." (PMID 27537359, 2016). "The improvement of insulin sensitivity might be implicated in the protection against type 2 diabetes associated with moderate wine drinking." (PMID 27231920, 2016). "Thus, lipid-induced inflammatory mediators establish a vicious positive feedback loop and sustain chronic inflammation in obese WAT, leading to loss of insulin sensitivity and type 2 diabetes (T2D)." (PMID 27684068, 2016). "RS may be an appropriate dietary ingredient to improve insulin sensitivity in women, particularly those at elevated risk for type 2 diabetes, such as African-American and post-menopausal women." (PMID 26766961, 2016). "Diets containing rapidly absorbing carbohydrates and low in dietary fiber (DF) are associated with increased risk of type 2 diabetes, whereas consumption of whole grain cereal foods reduces the risk of type 2 diabetes and heart disease, possibly partly via the effects on insulin metabolism." (PMID 28231119, 2016). "Therefore, an imbalance between the need for insulin and the ability to secrete insulin can cause type 2 diabetes." (PMID 27441644, 2016). "If the stimulus is insulin, then it is a kind of insulin resistance that may underline pathogenesis of type 2 diabetes." (PMID 26950111, 2016). "Additionally, Type 2 diabetes is associated with impaired metabolic flexibility, i.e., inability to switch from fatty acid to glucose oxidation in response to insulin." (PMID 28248217, 2016). "Women with PCOS are often insulin resistant and, as a consequence, may have high insulin levels, with increased risk for type 2 diabetes, high cholesterol, and high blood pressure." (PMID 27034774, 2016). "Dysregulation of SOCS-3 signaling may contribute to the development of type 2 diabetes in obese individuals whose β-cells become resistant to leptin signaling, leading to chronic insulin hypersecretion that eventually causes β-cell failure." (PMID 27242781, 2016). "Indeed, we and others have shown that in type 2 diabetes patients an exercise-induced improvement in insulin sensitivity is associated with an improvement in mitochondrial function." (PMID 27591854, 2016). "The environmental etiology of type 2 diabetes appears strongly mediated by oxidative stress, which, on the one hand, provokes insulin resistance, and, on the other hand, contributes to beta-cell damage and eventual deficiency in insulin secretion." (PMID 27458578, 2016). "Both leptin and insulin are known to be associated with body composition, BMI, and type 2 diabetes." (PMID 26964035, 2016). "This study investigated whether human insulin use might be associated with breast cancer risk in Taiwanese women with type 2 diabetes." (PMID 26537234, 2015). "He argued that genes that allow for rapid and efficient metabolism of food due to an overproduction of insulin, and thus an increased risk for type 2 diabetes in the presence of certain diets, were likely to be beneficial among hunter-gatherers when food was scarce." (PMID 26170196, 2015). "Despite the observed insulin cost savings associated with detemir, future studies should also determine overall costs (including indirect) and benefits associated with switching from glargine to detemir among Veteran with Type 2 diabetes." (PMID 26120575, 2015). "Indeed, a very recent study found that higher insulin exposure in type 2 diabetics is associated with a threefold increase in cardiovascular events." (PMID 26682540, 2015).
type 2 diabetes (continued). "The impaired ghrelin suppression after meals may partly cause impaired insulin secretion and postprandial hyperglycemia in type 2 diabetes." (PMID 26370322, 2015). "Because literature suggests that weight fluctuation increases the risk of type 2 diabetes in American women, the observed fluctuation among the patient group may have affected their insulin resistance." (PMID 26215867, 2015). "GDM and type 2 diabetes shared a similar pathophysiology, characterized by deficiency in islet β cell secretion and insulin sensitivity, and GDM was a stress situation that may reveal predisposition to type 2 diabetes." (PMID 26405461, 2015). "In general, a “western” dietary pattern that includes red and processed meats, foods, and beverages with high sugar content, refined grains, high fat and fried foods, and/or excessive snacking appears to elevate the risk of type 2 diabetes as well as insulin resistance." (PMID 26240831, 2015). "In addition, East Asians, including the Japanese, are known to have limited innate capacity for insulin secretion, resulting in greater susceptibility to type 2 diabetes than Caucasians." (PMID 26030122, 2015). "This again may be indicative of the well documented pioglitazone-induced decreases in hepatic fat content in type 2 diabetic patients, and its associated changes in insulin clearance." (PMID 25954816, 2015). "Finally, higher age was related to a lower odds of hypoglycemic events, e.g. a 10-year increase of age was associated with a 20% lower risk of hypoglycemia in the insulin-treated type 2 diabetes patients." (PMID 25698911, 2015). "Loss of insulin sensitivity in its target organs such as adipocytes, liver or skeletal muscle leads to improper storage and utilization of glucose and lipids which contribute towards the pathogenesis of both type II diabetes and metabolic syndrome." (PMID 25714093, 2015). "Human genetic studies have demonstrated that quantitative human anthropometric and metabolic traits, including body mass index, waist-hip ratio, and plasma concentrations of glucose and insulin, are highly heritable, and are established risk factors for type 2 diabetes and cardiovascular diseases." (PMID 26132169, 2015). "The presence of insulin signaling pathway components in the lists may also explain many previous observations on the causative role of JNK in type II diabetes." (PMID 26538579, 2015). "Ultimately, the importance of these alcohol-induced effects on insulin action and glucose homeostasis will need to be assessed in the context of whether they significantly alter the risk for the development of type 2 diabetes and other metabolic disturbances." (PMID 26426068, 2015). "Likewise, circulating chemerin tended to be positively associated with HOMA-β as a surrogate marker of fasting insulin secretion in Japanese patients with metabolic syndrome or type 2 diabetes." (PMID 25933030, 2015). "The recent genome-wide association studies have identified much more new loci that are implicated in β-cell development and function than those implicated in insulin action, highlighting insulin secretion in the development of type 2 diabetes in humans as well." (PMID 25946019, 2015). "Insulin, and insulin-like growth factors (IGFs) which are increased during much of the course of type II diabetes, could also increase cancer risk." (PMID 26250516, 2015). "Skeletal muscle is the major site of insulin-mediated glucose uptake and insulin resistance in this tissue causes metabolic syndrome and is recognized as the initial metabolic defect for the development of type 2 diabetes." (PMID 25993470, 2015). "Insulin levels could mediate in part a positive association between type 2 diabetes and elevated BMD." (PMID 25648962, 2015).
type 2 diabetes (continued). "Observational and limited intervention studies suggest that vitamin D might improve insulin sensitivity and secretion, mainly via its anti-inflammatory properties, thereby decreasing the risk of development and progression of type 2 diabetes." (PMID 26246241, 2015). "However, insulin dependency develops at an earlier stage than in type 2 diabetes, and patients in the insulinopenic state are at risk for ketoacidosis." (PMID 25834574, 2015). "Regulation of ENaC byphosphoinositides may underlie insulin (INS, P01308)‐evoked renalNa+ retention that can complicate the clinical management of type 2diabetes using insulin‐sensitizing thiazolidinedione drugs." (PMID 26650440, 2015). "The impaired MEF2 binding to PGC-1α may then also explain the observation that carriers of the Gly482Ser SNP exhibit a reduced insulin sensitivity and a higher risk for metabolic syndrome and type 2 diabetes." (PMID 25886402, 2015). "Unraveling the molecular mechanism underlying increased insulin secretion in LKB1-deficient β cells may open new therapeutic approaches for type 2 diabetes." (PMID 26139601, 2015). "The involvement of APSL at the N-terminus of TBC1D15 also demonstrates that this protein might be involved in insulin signaling and may be associated with the development of type 2 diabetes." (PMID 25984991, 2015). "Insulin-regulated glucose metabolism is mainly accomplished by skeletal muscle in humans, and insulin resistance (IR) in skeletal muscle is a main cause of type 2 diabetes (T2D)." (PMID 26942218, 2015). "In a longitudinal study, Weili Xu and colleagues explore whether variants in two insulin pathway genes modify the association of type 2 diabetes with dementia and AD." (PMID 26173052, 2015). "Reduced insulin transcription and dedifferentiation have been implicated in type 2 diabetes, making drugs that could reverse these processes potentially useful." (PMID 27019722, 2015). "TMEM27 and BACE2 expression might be involved in regulating the β-cell number not only in a disease state like type 2 diabetes but also in other conditions associated with increased insulin demand such as the metabolic syndrome or obesity." (PMID 24905913, 2014). "We have demonstrated that gestational diabetes may impair fetal insulin sensitivity and thus “program” the susceptibility to type 2 diabetes; this finding has been validated recently in an independent cohort." (PMID 24454790, 2014). "Impaired insulin secretion is a hallmark of type 2 diabetes (T2D)." (PMID 24603685, 2014). "Consequently, genome- and exome-wide analyses of rare genetic variation have identified novel genes implicated in high-density lipoprotein cholesterol, insulin processing and secretion, and type 2 diabetes." (PMID 24916163, 2014). "In conclusion, low circulating fetal DHA levels are associated with compromised fetal insulin sensitivity, and may be involved in “programming” the susceptibility to type 2 diabetes in the offspring of gestational diabetic women." (PMID 24454790, 2014). "However, the first detectable defect in individuals predisposed to type 2 diabetes is altered responsiveness of skeletal muscle to insulin, the principal site for insulin-stimulated glucose disposal." (PMID 24849570, 2014). "Impaired insulin action (insulin resistance) is a key risk factor for type 2 diabetes." (PMID 25368121, 2014). "This may be due to the relatively narrow range of fasting glucose (3.94–6.84 mmol/L) and insulin (3.0–22.32 mU/mL) levels that we observed, which are below the diagnostic threshold for type 2 diabetes." (PMID 24659234, 2014). "Subsequently, the multiple comorbidities of obesity, prediabetes, and type 2 diabetes that are attributed to insulin deficiency may actually stem in part from insulin excess." (PMID 25486190, 2014). "Type 2 diabetes is caused by insulin resistance (IR) and/or impaired insulin secretion." (PMID 24704640, 2014).
type 2 diabetes (continued). "Metformin can lower elevated insulin levels associated with type 2 diabetes by inhibiting hepatic gluconeogenesis via AMPK activation, and increases insulin sensitivity and glucose utilization by skeletal muscle and adipose tissue resulting in reduced blood glucose and insulin levels." (PMID 24858012, 2014). "Furthermore, it has recently also been shown that low insulin secretion is associated with increased incidence of hypertension in studies of families at genetic risk of type 2 diabetes." (PMID 25150967, 2014). "Second, this phenomenon provides a mechanism accounting for the increase in plasma FGF21 concentration and hepatic FGF21 mRNA abundance observed in animals and patients with type 2 diabetes, a condition that is associated with an elevation in the plasma concentration of both glucagon and insulin." (PMID 24733293, 2014). "Low circulating DHA levels are associated with compromised fetal insulin sensitivity, and may be involved in perinatally “programming” the susceptibility to type 2 diabetes in the offspring of gestational diabetic mothers." (PMID 24454790, 2014). "CDKAL1-related variants have previously been associated with type 2 diabetes and insulin response." (PMID 24695378, 2014). "Reduced insulin sensitivity is a predictor of incident type 2 diabetes and atherosclerotic risk." (PMID 24555815, 2014). "The aim of the study was to investigate the hypothesis that cumulative exposure to insulin and long-acting insulin analogs in previously oral treated type 2 diabetes patients might be associated with increased cancer mortality." (PMID 24667573, 2014). "Our study enrolling type 2 diabetic patients revealed that some amino acids and amino acid indices evaluating visceral fat obesity were strongly associated with insulin-related variables and plasma adiponectin levels, which are risk factors for developing cardiovascular diseases." (PMID 25177913, 2014). "Interestingly, type 2 diabetic patients have an up-regulated plasma myostatin associated with increased body mass index, higher fasting plasma glucose, and blood insulin sensitivity." (PMID 25279796, 2014). "In conclusion, type 2 diabetes patients with severe and acute hyperglycemia achieved better glycemic control with the basal-bolus regimen than with sliding-scale insulin, and factors associated with the insulin regimen used could be identified." (PMID 25181406, 2014). "In this study, we found a more significant association between the combined treatment of sulfonylurea plus metformin and a higher prevalence of vitamin B12 deficiency in patients with type 2 diabetes compared with that found for the insulin plus metformin combination therapy." (PMID 25299054, 2014). "Decreased adipocyte size has also been associated with increased insulin sensitivity, a reduced incidence of type II diabetes in rats and humans as well as reduced expression and release of adipocytokines, suggestive of a less detrimental phenotype associated with the smaller adipocytes." (PMID 24886466, 2014). "However, recent findings in humans show that HDL-raising interventions are associated with an increase in insulin sensitivity in patients with type 2 diabetes." (PMID 24347528, 2014). "So the insulin may cause the prostatic growth during type-2 diabetes by activating the IGF receptor." (PMID 25332855, 2014). "Thus, the aim of this study was to investigate the effect of sulfonylurea or insulin on vitamin B12 deficiency when used as a combinatorial therapy with metformin for patients with type 2 diabetes." (PMID 25299054, 2014). "The trend of lung cancer incidence in Taiwan is unknown, and the association between type 2 diabetes/insulin use and lung cancer is rarely studied." (PMID 24991802, 2014).